SMARCB1 (SWI/SNF related BAF chromatin remodeling complex subunit B1)
Diseases named in the same sentence as SMARCB1 in open-access papers (continued):
Sharing a sentence is not in itself a finding about the gene and the disease.
rhabdoid tumor (continued). "SMARCB1-negative tumors undoubtedly characterize hepatic rhabdoid tumors and unveil features similar to those of rhabdoid tumors, such as higher stage at diagnosis, chromosomal deletions or translocations of 22q11, and low serum AFP levels." (PMID 37600579, 2023). "The lack of or negative expression of SMARCB1/INI1 was considered the predominant event in the development of pediatric rhabdoid tumors." (PMID 37239344, 2023). "None harbored mutation or deletion of the SMARCB1 or SMARCA4 genes, thereby distinguishing these tumors from atypical teratoid/rhabdoid tumors." (PMID 36437415, 2023). "SMARCB1 is a tumor suppressor that has been characterized as absent in several pediatric tumors, such as malignant rhabdoid tumor (MRT) and atypical teratoid/rhabdoid tumor (AT/RT)." (PMID 35806102, 2022). "Rhabdoid tumors (RTs) of the brain (atypical teratoid/rhabdoid tumor; AT/RT) and extracranial sites (most often the kidney; RTK) are malignant tumors predominantly occurring in children, frequently those with SMARCB1 germline alterations." (PMID 35912263, 2022). "These lesions exhibit many features of rhabdoid tumors, such as rhabdoid cells and complete absence of Smarcb1 expression." (PMID 33918045, 2021). "SMARCA2, SMARCA4, SMARCB1, ARID1A, ARID1B, and PBRM1 are subunits of the Switch/Sucrose non-fermenting (SWI/SNF) complex, which show frequent alterations in rhabdoid tumors, ovarian clear cell carcinomas (OCCCs), and small-cell carcinoma of the ovary, hyper-calcemic type (SCCOHT)." (PMID 34359794, 2021). "In a murine model, knockout of SMARCB1 led to rhabdoid tumors in soft tissues but never in the brain." (PMID 31462227, 2019). "Of note, EZH2 inhibitors seem to be particularly active in malignant rhabdoid tumors, which are deficient in the Switch/Sucrose NonFermentable (SWI/SNF) chromatin remodeling complexes INI1 (SMARCB1)." (PMID 29575713, 2018). "Some examples of the SWI/SNF-PRC2/EZH2 oncogenesis hypothesis include malignant rhabdoid tumors (MRT) in which the SWI/SNF subunit INI1 (a.k.a. hSNF5, SMARCB1, BAF47) is inactivated, and in lymphomas with EZH2 activating mutations." (PMID 27125524, 2016). "Interestingly, we observed that all tumor cells showed the complete loss of nuclear staining for SMARCB1 in both the organoid and non-adhesive areas with rhabdoid cells compared with the ubiquitous expression of SMARCB1 in surrounding normal tissue, indicating a renal malignant rhabdoid tumor." (PMID 27733182, 2016). "As such, inhibitors of EZH2 are now being tested in the clinic, and objective responses have been observed in SMARCB1-negative rhabdoid tumors in the setting of a Phase I study." (PMID 27391784, 2016). "In our initial studies using CRISPR-Cas9 to verify the dependence on EZH2 activity for proliferation of a SMARCB1/SNF5/INI1 mutant malignant rhabdoid tumor (MRT) cell line, we noted that the initial reduction in proliferation was lost over time." (PMID 26578851, 2015). "The main differential diagnosis is with the malignant rhabdoid tumors (MRT), a neoplasm more common in childhood and characterized by genetic inactivation of SMARCB1 (SNF5, INI-1), a component of the SWI/SNF chromatin remodelling complex or deletions of chromosome 22q." (PMID 23425390, 2013). "Some pathways drivingoncogenesis are defined in rhabdoid tumors: In SMARCB1 negative tumors oncogenes (including MYC and CYCLIND1) and tumor cascades such as the sonic hedgehog pathway are activated." (PMID 23764045, 2013). "In these circumstances other diagnostic parameters including negative SMARCB1 protein staining should be used as a guide to assess the likelihood that pathogenic mutations may have been missed and to the possibility of homozygous deletion of the gene, present in up to 20% of rhabdoid tumors." (PMID 20003390, 2009).
rhabdoid tumor (continued). "We identified minor transcriptional upregulation of CDKN1A or CDKN1B in two different RT cell backgrounds following transfection with SMARCB1 however, expression of these genes persisted in clinical specimens of ATRT with inactivated SMARCB1 arguing against a major role in rhabdoid tumor aetiology." (PMID 19221586, 2009). "Unlike primary rhabdoid tumors, such as malignant rhabdoid tumors, atypical teratoid/rhabdoid tumors, SMARCA4-deficient thoracic sarcomas, and epithelioid sarcoma, which often show alterations in SMARCB1 (INI1) or SMARCA4, cutaneous RSCC does not exhibit such inactivation." (PMID 39677213, 2024). "Inhibition of the growth of rhabdoid tumors with lack of the SMARCB1, through knockdown of the SWI/SNF catalytic subunit SMARCA4, suggests that the survival of such tumor cells may depend on the residual activity of the SWI/SNF complex." (PMID 37175555, 2023). "In addition, FISH for an EWSR1 break-apart can be misleading in malignant rhabdoid tumors (MRTs) in which commonly the genetic region encompassing SMARCB1 is deleted that may involve the EWSR1 gene, which is located close to SMARCB1 on chr22." (PMID 33919988, 2021). "Loss of nuclear SMARCB1 (INI1/hSNF5/BAF47) protein expression due to biallelic mutations of the SMARCB1 tumor suppressor gene is a hallmark of atypical teratoid/rhabdoid tumors (ATRT), but the presence of cytoplasmic SMARCB1 protein in these tumors has not yet been described." (PMID 34003336, 2021). "Even though EZH2 has been pursued as a therapeutic target for several types of tumors, such as sarcoma, lymphoma, and malignant rhabdoid tumor (MRT), there is still much unknown how SMARCB1/INI1 drives EZH2 or how SMARCB1 interacts with the potential targets in pancreatic cancer." (PMID 34315468, 2021). "Furthermore, SMARCB1 is a core member of the SWI/SNF complex where alterations of one or more members have been identified in up to 20% of all cancers including malignant rhabdoid tumors (MRTs) and atypical teratoid rhabdoid tumors (ATRTs)." (PMID 30860482, 2019). "The SMARCB1 deficiency observed in the synovial sarcoma cell lines could be distinguished from the SMARCB1-negative malignant rhabdoid tumor (MRT) cell line, G401." (PMID 27391784, 2016). "Treatment with EPZ-6438 caused also apoptosis in cell lines and dose-dependent tumor regression in xenograft model of malignant rhabdoid tumors with mutated SMARCB1 (also known as SNF5, INI1, and BAF47), a subunit of the SWItch/sucrose non-fermentable (SWI/SNF) chromatin remodeling complex." (PMID 27222667, 2016). "However, the cell of origin of rhabdoid tumor being unknown, we could not directly compare re-expressed levels of SMARCB1 to original levels." (PMID 39542244, 2024). "In SMARCB1-null rhabdoid tumors, the presence of BRG1 and the non-canonical SWI/SNF subunit, BRD9, are synthetic lethal targets in rhabdoid cancers, although the mechanisms by which they maintain a rogue gene expression program are not entirely clear." (PMID 38473277, 2024). "Interactions between SMARCB1/INI-1 and key protein components in various cellular pathways are related to tumor progression and proliferation.SMARCB1/INI-1 protein was undetectable in rhabdoid tumor cells, whereas non-tumorous cells express the SMARCB1/INI-1 genes." (PMID 33680622, 2021). "Comparing protein expression in different SMARCB1 negative rhabdoid tumor cell lines (A204, G401, BT16, BT12) with ESCs (OG2; as a control with known highly expressed HDAC1 and HDAC2) demonstrate that group 1 HDAC levels are similarly expressed in rhabdoid tumors and ESC." (PMID 23764045, 2013).
epithelioid sarcoma (126 papers, 2011 to 2026). An aggressive malignant neoplasm of uncertain differentiation, characterized by the presence of epithelioid cells forming nodular patterns. "Loss of the SMARCB1 gene has been linked to various neoplasms, including rhabdoid tumours (RTs), epithelioid sarcoma, and renal medullary carcinoma." (PMID 40422882, 2025). "Tazemetostat is traditionally used in the treatment of epithelioid sarcoma with INI1/SMARCB1 loss of function, which also characterizes ATRTs." (PMID 40052132, 2025). "EZH2 inhibition is an effective therapeutic strategy in epithelioid sarcomas that have a loss of SMARCB1, a subunit of SWI/SNF complex that opposes the activity of EZH215." (PMID 39789291, 2025). "In another case, approximately 90% of epithelioid sarcomas (ESs) show loss of integrase interactor 1 (INI1) function due to biallelic inactivation of the SMARCB1 gene on chromosome 22q11.2." (PMID 40227789, 2025). "Tazemetostat, an inhibitor of EZH2, has received FDA approval for treatment of SMARCB1-deficient epithelioid sarcoma, and trials for other malignancies, including RTs, are ongoing." (PMID 40422882, 2025). "Certain subtypes, such as epithelioid sarcomas with SMARCB1 mutations, exhibit low ORRs to targeted therapies, such as the 15% response rate observed with tazemetostat." (PMID 40054460, 2025). "A phase II trial (NCT04416568) is currently recruiting patients to investigate the combination of nivolumab (anti-PD1) with ipilimumab (anti-CTLA4) in children and young adults with SMARCB1-deficient tumours, including RTs, epithelioid sarcomas, and chordomas." (PMID 40422882, 2025). "In a phase II trial of EZH2-inhibitor tazemetostat for people > 16 years with SMARCB1-deficient advanced epithelioid sarcoma, 15% had an objective response and the median progression-free survival was 5.5 months, prompting FDA approval." (PMID 40983796, 2025). "These include ALK fusions in inflammatory myofibroblastic tumors, COLIA1-PDGFB fusions in dermatofibrosarcoma protuberans and INI1/SMARCB1 mutations/deletions in epithelioid sarcoma." (PMID 40505420, 2025). "Based on this promising preclinical data, an ongoing phase II clinical trial of tazemetostat in patients with advanced epithelioid sarcoma with loss of INI1/SMARCB1 will evaluate the clinical relevance of targeting this epigenetic axis in patients with SCCOTH." (PMID 40896427, 2025). "FISH analysis of the thigh mass identified SMARCB1/INI1 gene deletion, confirming the diagnosis of INI1-deficient epithelioid sarcoma." (PMID 40830970, 2025). "In an open-label, phase 2 basket study, 62 patients with epithelioid sarcoma characterized by INI1/SMARCB1 loss were enrolled." (PMID 40115023, 2025). "Tazemetostat, an EZH2 inhibitor, was tested in patients with locally advanced or metastatic epithelioid sarcoma with documented loss of INI1 expression with IHC or biallelic SMARCB1 alterations in a Phase 2 trial." (PMID 39796641, 2024). "Epithelioid sarcoma (ES) is an ultra-rare tumour representing less than 1% of STS characterised by loss of the tumour suppressor INI1 (SMARCB1), a subunit of the SWI/SNF chromatin complex, on IHC in 90% of cases." (PMID 39796641, 2024). "Another patient with advanced refractory, SMARCB1-deficient epithelioid sarcoma achieved complete remission with combined ipilimumab and nivolumab." (PMID 38217014, 2024). "It has become an approved drug in the United States for treating SMARCB1-deficient epithelioid sarcoma." (PMID 38836164, 2024). "SMARCB1 is a gene known to cause carcinogenesis in many soft tissue tumors, including malignant rhabdoid tumors and epithelioid sarcoma." (PMID 38836164, 2024). "Epithelioid sarcoma (EpS) is an aggressive mesenchymal tumour, characterised by the loss of expression of SMARCB1, a key member of the SWItch/Sucrose Non‐Fermentable (SWI/SNF) chromatin remodelling complex." (PMID 37316954, 2023).
epithelioid sarcoma (continued). "Loss of expression of SMARCB1 is described in the epithelioid sarcomas, epithelioid malignant peripheral nerve sheath tumors, and kidney medullary carcinomas." (PMID 37974295, 2023). "Epithelioid sarcoma is a rare and aggressive mesenchymal tumour, the genetic hallmark of which is the loss of expression of SMARCB1, a key member of the SWItch/Sucrose Non‐Fermentable (SWI/SNF) chromatin remodelling complex." (PMID 37316954, 2023). "Loss-of-function mutations in SMARCB1 have been identified as a cause of various histologic tumors, including epithelioid sarcomas, schwannomatosis, synovial sarcomas, and myoepithelial carcinomas." (PMID 37974295, 2023). "INI1 (encoded by the SMARCB1 tumor suppressor gene) is a core subunit of the switch/sucrose nonfermentable (SWI/SNF) chromatin remodeling complex frequently inactivated in epithelioid sarcomas." (PMID 36209184, 2022). "Tazemetostat has recently received FDA approval for the treatment of SMARCB1-deficient epithelioid sarcoma." (PMID 35892904, 2022). "Recently, in a phase II basket trial, a selective inhibitor of EZH2, tazemetostat, showed clinical activity in patients with advanced epithelioid sarcoma with loss of INI-1/SMARCB1." (PMID 36431263, 2022). "An EZH2 inhibitor, tazemetostat, just gained approval for treatment of epithelioid sarcoma harboring SMARCB1 loss in January 2020 in the USA." (PMID 33481850, 2021). "In epithelioid sarcoma, the sensitivity to tazemetostat is associated with a loss of SMARCB1, a component of the SWI/SNF remodeling complex of Trithorax group (TrxG) proteins that antagonize PcG repression." (PMID 34202528, 2021). "Epithelioid sarcoma (ES) is characterized by the loss of SMARCB1/INI1 (integrase interactor 1) or other proteins of the SWI/SNF complex." (PMID 32751241, 2020). "The loss of SMARCB1/INI1 protein in epithelioid sarcoma is tumor-promoting and is currently used in the clinic as a biomarker for differential diagnosis." (PMID 33072594, 2020). "Epithelioid sarcomas often show nodular growth with central necrosis and loss of SMARCB1 (INI1) expression." (PMID 32316685, 2020). "Our findings have implications for other cancer types that harbor SMARCB1 deficiencies, including epithelioid sarcomas, renal medullary carcinoma, epithelioid malignant peripheral nerve sheath tumors, and extraskeletal myxoid chondrosarcomas." (PMID 27783942, 2016). "They concluded that the epigenetic mechanism of gene silencing by miRNAs caused the loss of SMARCB1 expression in epithelioid sarcoma." (PMID 25165708, 2014). "Deletions at chromosome 22 or loss of SMARCB1/INI1 expression have also been implicated in the pathogenesis of additional tumor types: renal medullary carcinomas, epithelioid sarcomas, myoepithelial carcinomas and extraskeletal myxoid chondrosarcomas." (PMID 24286138, 2013). "Epithelioid sarcoma is a rare soft tissue sarcoma characterized by SMARCB1/INI1 deficiency." (PMID 38310286, 2024). "However, epithelioid sarcoma is SMARCB1-deficient with retained SMARCA2 expression, and the expression of SOX2 and SALL4 is deficient." (PMID 38347129, 2024). "Over 90% of epithelioid sarcoma cases are characterized by loss of INI1 (also known as SMARCB1), conferring an oncogenic dependency on the enhancer of zeste homolog 2 (EZH2), the catalytic subunit of the chromatin remodeling polycomb repressive complex 2 (PRC2)." (PMID 37998367, 2023). "Finally, while SMARCB1 deletion is a typical feature of epithelioid sarcoma, the SMARCA4 deletion mutation is only found in SDUS." (PMID 37194064, 2023). "In addition, SMARCA4 loss of expression can also be observed in tumors more commonly associated with SMARCB1 loss, such as epithelioid sarcoma." (PMID 33921435, 2021).
epithelioid sarcoma (continued). "Over 90% of ES, both conventional and proximal type, shows a complete SMARC1/INI1 (integrase interactor 1) loss due to the biallelic deletion of the SMARCB1 gene locus or as a consequence of epigenetic dysregulation, which defines both types of epithelioid sarcoma." (PMID 32751241, 2020). "Epithelioid sarcoma (ES) is a rare mesenchymal malignancy marked by SMARCB1/INI1 deficiency." (PMID 31331120, 2019). "Besides targeting the genomic alteration, epigenetic regulators such as DNA methylation, histone modification and microRNA are emerging potential targets against sarcomas including tazemetostat, an EZH2 inhibitor for epithelioid sarcoma with loss of SMARCB1/INI1/BAF47." (PMID 38434982, 2024). "The polycomb repressive complex EZH2 inhibitor tazemetostat was recently approved for the treatment of SMARCB1-deficient epithelioid sarcomas, based on the functional antagonism between PRC2 and SMARCB1." (PMID 40794452, 2025). "A study in head and neck cancer found deletions of SMARCA4 as one of the most common occurrences in patients responding to ICI, and there have been also reports of complete remission in a patient with stage IV SMARCB1-inactivated epithelioid sarcoma." (PMID 39813356, 2025). "In 2020, a phase II trial for progressive epithelioid sarcoma with a SMARCB1 deficit was conducted and was shown to be effective." (PMID 39398818, 2024). "SMARCB1 (BAF47/INI1) deletion has been found in several malignant tumors including epithelioid sarcoma." (PMID 38434982, 2024). "Studies have shown that epithelioid sarcomas are characterized by genetic aberrations in the SMARCB1 (INI-1) gene, which is a potent tumor suppressor gene and part of the SWI/SNF complex." (PMID 36980578, 2023). "To test the ability of pevonedistat to inhibit RMC and other SMARCB1‐deficient cell lines, we performed MTT assays on two RMC cell lines (RMC2C and RMC219) and in G‐401 (MRT) and VA‐ES‐BJ (epithelioid sarcoma) cell lines." (PMID 37226898, 2023). "Epithelioid sarcoma can show rhabdoid and spindle morphology with tumor necrosis, they generally express epithelial markers and CD34, and loss SMARCB1/INII1 expression and don’t express Myo-D1 and Myogenin." (PMID 36998041, 2023). "A trial was performed in patients with epithelioid sarcomas (nearly all tumors have homozygous deletion of SMARCB1), which demonstrated a response rate of 15%, and of the patients who responded, 67% had a response lasting 6 months or longer." (PMID 35409155, 2022). "In particular, the SWI/SNF subunit SMARCB1 has been approved as an effective marker of metastatic or locally advanced epithelioid sarcoma sensitivity to tazemetostat, while SMARCA2, SMARCA4, ARID1A, and PBRM1 are potential marker candidates." (PMID 34202528, 2021). "A loss of SMARCB1/INI1 protein is shown in almost all epithelioid sarcoma (ES) and 50% of MPNSTs." (PMID 34068344, 2021). "Recently, aberrant expression of SMARCB1/INI1 has been found in various tumors such as epithelioid sarcomas, schwannomatosis, synovial sarcomas, and so on." (PMID 34068344, 2021). "The epithelioid sarcoma (for which tazemetostat has been approved by the FDA) is deficient in the SMARCB1 (also known as INI1 or SNF5) subunit of the SWI/SNF family." (PMID 34202528, 2021). "Due to the loss of expression of the INI1/SMARCB1, MELTVR need to be differentiated from INI1/SMARCB1-deficient vulvar neoplasms, including epithelioid sarcoma and extrarenal malignant rhabdoid tumor (E-MRT)." (PMID 31915021, 2020). "While several clinical trials are testing these potential dependencies in patients, early in 2020 the EZH2i tazemetostat received for the first time FDA approval for the treatment of epithelioid sarcomas with SMARCB1/INI1 deletions." (PMID 34968293, 2020). "Thereafter SMARCB1 gene alternations were identified in other malignant tumors, such as epithelioid sarcoma, myoepithelial carcinoma." (PMID 29625594, 2018).